USP9X (ubiquitin specific peptidase 9 X-linked)
Description:
Deubiquitinase involved both in the processing of ubiquitin precursors and of ubiquitinated proteins. May therefore play an important regulatory role at the level of protein turnover by preventing degradation of proteins through the removal of conjugated ubiquitin. Specifically hydrolyzes 'Lys-11'-, followed by 'Lys-63'-, 'Lys-48'- and 'Lys-6'-linked polyubiquitins chains. Essential component of TGF-beta/BMP signaling cascade. Specifically deubiquitinates monoubiquitinated SMAD4, opposing the activity of E3 ubiquitin-protein ligase TRIM33. Deubiquitinates alkylation repair enzyme ALKBH3. OTUD4 recruits USP7 and USP9X to stabilize ALKBH3, thereby promoting the repair of alkylated DNA lesions. Deubiquitinates RNA demethylase enzyme ALKBH5, promoting its stability. Deubiquitinates mTORC2 complex component RICTOR at 'Lys-294' by removing 'Lys-63'-linked polyubiquitin chains, stabilizing RICTOR and enhancing its binding to MTOR, thus promoting mTORC2 complex assembly. Regulates chromosome alignment and segregation in mitosis by regulating the localization of BIRC5/survivin to mitotic centromeres. Involved in axonal growth and neuronal cell migration. Regulates cellular clock function by enhancing the protein stability and transcriptional activity of the core circadian protein BMAL1 via its deubiquitinating activity. Acts as a regulator of peroxisome import by mediating deubiquitination of PEX5: specifically deubiquitinates PEX5 monoubiquitinated at 'Cys-11' following its retrotranslocation into the cytosol, resetting PEX5 for a subsequent import cycle. Deubiquitinates PEG10 (By similarity). Inhibits the activation of the Hippo signaling pathway via deubiquitination of AMOTL2 at 'Lys-347' and 'Lys-408' which prohibits its interaction with and activation of LATS2. Loss of LATS2 activation and subsequent loss of YAP1 phosphorylation results in an increase in YAP1-driven transcription of target genes.
Synonyms: hFAM; DFFRX; FAM; FAF; FAF-X; MRX99; MRXS99F; XLID99
Tractability: Small molecule: a high-quality ligand is known. PROTAC: ubiquitination databases record sites on it; its protein half-life has been measured; a small molecule that binds it is known.
Target class: Cysteine protease; Cysteine protease CA clan; Protease; Enzyme; Cysteine protease C19 family
Gene: Protein-coding gene on chromosome X (41,085,431 to 41,236,579, forward strand). Ensembl gene ENSG00000124486.
Subcellular location: Cytoplasm, cytosol; Cell projection, growth cone; Cytoplasm, cytoskeleton, cilium axoneme
Subcellular location (Human Protein Atlas): Cytosol
Pathways (Reactome):
Metabolism of proteins: Amyloid fiber formation; Synthesis of active ubiquitin: roles of E1 and E2 enzymes; Ub-specific processing proteases
Signal Transduction: Downregulation of SMAD2/3:SMAD4 transcriptional activity; RHOU GTPase cycle; RHOV GTPase cycle
Protein localization: Peroxisomal protein import
Gene Ontology:
Molecular function: co-SMAD binding; cysteine-type deubiquitinase activity; deubiquitinase activity; K11-linked deubiquitinase activity; K48-linked deubiquitinase activity; K63-linked deubiquitinase activity; molecular sequestering activity; protein binding; cysteine-type endopeptidase activity; cysteine-type peptidase activity
Biological process: axon extension; BMP signaling pathway; cilium assembly; cytosolic ciliogenesis; DNA alkylation repair; monoubiquitinated protein deubiquitination; negative regulation of proteasomal ubiquitin-dependent protein catabolic process; neuron migration; positive regulation of protein binding; positive regulation of TORC2 signaling; protein deubiquitination; protein deubiquitination involved in ubiquitin-dependent protein catabolic process; protein import into peroxisome matrix, receptor recycling; protein K63-linked deubiquitination; protein stabilization; regulation of circadian rhythm; transforming growth factor beta receptor signaling pathway; amyloid fibril formation; cell migration; female gamete generation; intracellular protein localization; negative regulation of transcription by RNA polymerase II; protein ubiquitination
Cellular component: centrosome; cilium; cytoplasm; cytosol; growth cone; membrane; axoneme
Gene-disease validity (ClinGen):
ClinGen rates the evidence that USP9X causes each of these diseases.
X-linked syndromic intellectual disability (X-linked): Definitive.
Homologues: Orthologues: chimpanzee USP9X (99% identical), macaque USP9X (99% identical), rabbit USP9X (99% identical), pig USP9X (99% identical), rat Usp9x (99% identical), mouse Usp9x (98% identical), guinea pig USP9X (98% identical), tropical clawed frog usp9x (93% identical), zebrafish usp9 (90% identical). Paralogues in human: USP9Y (92% identical), USP24 (12% identical), USP34 (9% identical), USP32 (9% identical), USP19 (8% identical), USP31 (8% identical), USP15 (8% identical), USP4 (8% identical), USP8 (8% identical), USP43 (7% identical), USP38 (7% identical), USP36 (7% identical), and 59 more.
Diseases named in the same sentence as USP9X in open-access papers:
USP9X is named in the same sentence as 160 diseases in open-access papers, as found by Europe PMC text mining. Sharing a sentence is not in itself a finding about the gene and the disease. The quoted sentences say what the papers report.
breast carcinoma (39 papers, 2014 to 2025). "This suggests that elevated Cep131 levels induced by loss of USP9X caused centrosome amplification and promoted breast cancer progression." (PMID 31358734, 2019). "It will be also important to investigate the mechanisms underlying USP9X dysregulation in breast cancer and the role of the USP9X/CEP131 axis in the development/progression of breast cancer." (PMID 28361952, 2017). "Mutations of USP9X have been found associated with intellectual disability and various types of cancers, such renal cell cancer, breast cancer and prostate cancer." (PMID 27517496, 2016). "Recently, it was shown that loss of USP9X function prevented tamoxifen-induced proliferation arrest in oestrogen receptor α-positive breast cancer cells." (PMID 25672900, 2015). "Some cancers, including primary breast cancer, demonstrate an association between USP9X and Mcl-1, a pro-survival BCL2 family member that is essential for stem and progenitor cell survival." (PMID 25606592, 2014). "Recently, it was reported that loss of USP9X function prevented tamoxifen-induced proliferation arrest in estrogen receptor positive breast cancer cells, which suggested that USP9X is closely involved in the endocrine therapy resistance of breast cancer." (PMID 34112167, 2021). "In addition, a recent study showed that elevated Cep131 levels induced by loss of deubiquitinase USP9X promoted centrosome amplification and breast cancer development." (PMID 31358734, 2019). "Nutrient deprivation or the induction of endoplasmic reticulum stress could upregulate TRIB3 expression in basal-like breast cancer through ubiquitin specific peptidase 9 X-linked (USP9x)-mediated deubiquitination and stabilization of TRIB3." (PMID 30678233, 2019). "In breast cancer, aggressive B-cell lymphoma and glioblastoma, USP9X alleviates tumor cell survival and confers chemoresistance through YAP1, XIAP or Mcl-1 stabilization." (PMID 40246814, 2025). "On the other hand, TGF-β signaling elevates the deubiquitinase activity of USP9X by phosphorylation in neurodevelopment and breast cancer metastasis." (PMID 40246814, 2025). "As an important DUB, USP9X regulates multi-types of cancer development, such as glioblastoma, lung cancer, colorectal cancer, and breast cancer, through mediating the stability of ALDH1A3, KDM4C, FBW7, CEP131, and Snail1." (PMID 40246814, 2025). "The up-regulation of YAP1 degradation upon elimination of USP9X enhances cellular sensitivity to chemotherapy, indicating the oncogenic role of USP9X and identifying it as a potential therapeutic target for breast cancer treatment." (PMID 40034124, 2025). "While USP7 affects the cell cycle of breast cancer, which regulates its growth, USP9X influences breast cancer growth by influencing nuclear replication." (PMID 38613804, 2024). "In a study on breast cancer, USP9x was found to promote chemoresistance through the stabilization of the transcriptional regulator YAP1." (PMID 39075050, 2024). "In breast cancer, USP9X deubiquitinates and stabilizes YAP to promote breast cancer cell proliferation and chemoresistance to therapeutic drugs." (PMID 37349820, 2023). "TRIB3 is positively associated with breast cancer stemness and progression by inhibiting FOXO1 degradation and increasing SOX2 transcription and the cellular stress-activated TRB3/USP9x-dependent Notch pathway in breast cancer." (PMID 36463181, 2022). "As FFA enhances TGF-β-promoted tumorigenesis through activation of ERK and USP9X, USP9X catalytic inhibitors such as WP1130 are regarded as effective treatments for obesity-related breast cancers." (PMID 34575114, 2021). "USP9X is overexpressed in breast cancer tissues, promoting tumor growth through the regulation of the cell cycle." (PMID 34575114, 2021). "TDRED3, in addition to its role in inhibiting apoptosis by interacting with USP9X, also plays a vital role in determining the invasive capacity of breast cancer cells." (PMID 34604242, 2021).
breast carcinoma (continued). "The authors mainly focused on the roles of several important DUBs in breast cancer, such as USP9X, USP15, and CYLD(Cylindromatosis tumor suppressor protein)." (PMID 34575114, 2021). "Upon cellular stress in basal-like breast cancer, USP9X is required for TRB3 upregulation and Notch activation." (PMID 33158118, 2020). "Deubiquitination of BCL9 by USP9X also promotes the proliferation and invasion of breast cancer cells, implying the role of USP9X in breast carcinogenesis." (PMID 33158118, 2020). "On the other hand, USP9X overexpression promotes centrosome amplification and carcinogenesis in breast carcinomas and resistance to mitotic-spindle-poison-containing chemotherapy in human B-cell lymphoma." (PMID 31671755, 2019). "Consistently, the expression level of USP9X was significantly higher in breast carcinoma samples than that in normal mammary tissues." (PMID 28361952, 2017). "Knockdown of TDRD3 expression in breast cancer cells decreases the level of MCL-1, a known USP9X substrate, and sensitizes breast cancer cells to chemotherapy drug-induced apoptosis." (PMID 28101374, 2017). "The protein abundance of PCM1 was indeed elevated in breast cancer and correlated with that of USP9X." (PMID 28361952, 2017). "Significantly, USP9X is overexpressed in breast carcinomas, and its level of expression is correlated with that of CEP131 and higher histologic grades of breast cancer." (PMID 28361952, 2017). "Our experiments identify USP9X as an important regulator of centrosome biogenesis and uncover a critical role for USP9X/CEP131 in breast carcinogenesis, supporting the pursuit of USP9X/CEP131 as potential targets for breast cancer intervention." (PMID 28361952, 2017). "There are some evidences suggesting USP9X promotes tumor development in a variety of neoplasms, such as hepatocellular carcinoma, breast cancer, prostate cancer and colorectal cancer." (PMID 27517496, 2016). "In SK-BR3 cells (breast cancer cells overexpressing ErbB2) treated with the proteasome inhibitor bortezomib, ErbB2 co-immunoprecipitates with a complex containing c-Cbl and USP9X." (PMID 25672900, 2015). "We have found that lentivirus-mediated USP9X knockdown in tumorigenic human breast cancer cell lines inhibits their growth." (PMID 25606592, 2014). "Moreover, USP9X-mediated deubiquitination of BCL9 enhances breast cancer cell proliferation and invasion, implicating its involvement in Wnt/β-catenin signaling and breast carcinogenesis." (PMID 40034124, 2025). "In addition, upregulation of USP9X can lead to the occurrence of breast cancer, and facilitates the progression of melanoma, esophageal squamous cell carcinoma, and lung cancer." (PMID 39075342, 2024). "This has been observed in breast cancer, where the deubiquitinating enzyme USP9X, an integral component of the centrosome and required for centriole duplication, causes excessive levels of CEP131, thereby contributing to the pathogenesis of breast cancer." (PMID 38606093, 2024). "Downregulation of USP9X reinforces cisplatin sensitivity in ER- breast cancer cells, which is speculated to be a result of the degradation of MCL1." (PMID 34575114, 2021). "A previous study found that USP9X could promote the occurrence of breast cancer by regulating CEp131." (PMID 34856948, 2021). "WP1130 also increases the cytotoxic effects of cisplatin partly via its inhibitory effect on USP9X in ER- breast cancer cells, suggesting combination therapy with WP1130 may be an efficient method for patients with ER- breast cancer." (PMID 34575114, 2021). "USP9X plays an important role in promoting breast cancer metastasis." (PMID 34575114, 2021). "YAP1 is deubiquitinated and stabilized by USP9X, accelerating cell proliferation in breast cancers." (PMID 34575114, 2021). "In addition, β-catenin was reported to interact with USP9x to inhibit the degradation of β-catenin through the deubiquitination of β-catenin in breast cancer." (PMID 32851100, 2020).
breast carcinoma (continued). "Our observations support a model in which overexpression of USP9X in breast cancer results in elevated CEP131 protein, which, in turn, leads to centrosome amplification and genome instability, and eventually contributes to the development/progression of breast cancer." (PMID 28361952, 2017). "Therefore, our study identifies TDRD3 as a regulator of USP9X and a potential target for therapeutic induction of apoptosis in breast cancer cells." (PMID 28101374, 2017). "Finally, we show that knockdown of TDRD3 expression sensitizes breast cancer cells to chemotherapeutic drug-induced apoptosis, likely due to its regulation of USP9X." (PMID 28101374, 2017). "This investigation may be particularly important because several mediators of breast cancer signaling and tumorigenicity, in addition to Mcl-1, are regulated by USP9X." (PMID 25606592, 2014). "Furthermore, the expression level of USP9X is positively related to LATS expression but negatively associated with the expression of YAP/TAZ in multiple tumor tissues, such as pancreatic cancer and breast cancer, demonstrating that USP9X potentiates LATS kinase in suppressing tumor growth." (PMID 30319415, 2018). "While several DUBs, such as USP10 and USP9X, have been reported to affect YAP1 ubiquitination in HCCs and breast cancers respectively, the deubiquitinating enzyme responsible for YAP1 regulation in CRC has remained unidentified." (PMID 39968498, 2025). "The vital interaction of USP9X and SMAD4 mediates free fatty acids (FFA)-induced aberrant TGF-β activation and obesity-promoted breast cancer metastasis." (PMID 40246814, 2025). "Conversely, deubiquitinase USP10 and USP9X stabilize YAP and promote cell growth and survival in HCC and breast cancer." (PMID 39968498, 2025). "In the context of deubiquitination studies, a recent investigation has revealed that USP9X specifically targets YAP1 for deubiquitination and stabilization, thereby facilitating breast cancer cell survival and progression." (PMID 40034124, 2025). "In terms of treatment, USPs can be used as cancer therapeutic targets, such as inhibitors of USP1, USP4, USP7, USP9X, and USP33 for prostate cancer, lung cancer, breast cancer, and hematological malignancies, among others." (PMID 38613804, 2024). "It has been previously reported that the deubiquitination enzyme USP9X deubiquitinates and stabilizes YAP in breast cancer cells, thus promoting cancer cell survival." (PMID 37349820, 2023). "For instance, recent data have indicated that USP9X promotes the activation of canonical Wnt signaling through deubiquitinating and stabilizing DVL2 in breast cancer cells." (PMID 37726816, 2023). "It has been recently reported that the deubiquitinase USP9X and RNF115 are correlatively upregulated in breast cancer tissue arrays and breast cancer cell lines." (PMID 35844553, 2022). "RNF115 is a novel substrate for USP9X, and the USP9X–RNF115 axis is involved in aggressive phenotypes by increasing breast cancer cell invasion and migration." (PMID 34575114, 2021). "In breast cancer, DUB USP9X strongly interacts with LATS kinase to regulate Hippo pathway and suppress tumor growth." (PMID 33456565, 2021). "The deubiquitinase USP9X stabilizes MCL1, whose overexpression contributes to chemoresistance and poor prognosis in breast cancer." (PMID 34575114, 2021). "An analysis of differential USP gene expression in breast cancer found greater than threefold overexpression of USP9X, USP10 and USP25 in human breast cancer tissue as compared with adjacent normal tissue." (PMID 25606592, 2014). "Besides HIF-2α, USP9X has been reported to inhibit degradation of the other key hypoxia factor, HIF-1α, in breast cancer." (PMID 40246814, 2025).
breast carcinoma (continued). "Detailed researches discovered that dyslipidemia interaction with USP9x and SMAD4 might govern TGF-β signaling during breast cancer metastasis." (PMID 39135158, 2024). "Interestingly, USP9X enhances the stability of a E3 ubiquitin ligase, RNF115, which has also been shown to promote cell proliferation in ERα+ breast cancers via downregulation of p21." (PMID 34575114, 2021). "Importantly, depletion of USP9X in MDAMB231 metastatic breast cancer cells, which have elevated SMURF1 expression, inhibits SMURF1-dependent breast cancer cell motility." (PMID 25606592, 2014). "Indeed, USP9X overexpression increased HIF-2α levels in a dose-dependent manner, without affecting the HIF-1α levels which has been reported as a USP9X substrate in breast cancer." (PMID 40246814, 2025). "WP1130 has been shown to increase the sensitivity of cancer cells, such as hepatocellular carcinoma cells, breast cancer cells, and pancreatic cancer cells, to chemotherapeutic agents by inhibiting USP9X activity, although no relevant clinical trials have been reported to date." (PMID 35389885, 2022). "USP9X has recently been suggested to stabilize the breast cancer protein-1 (BRCA1) required for DSB repair by homologous recombination through its DUB enzymatic activity, and which is required for resistance to the PARP inhibitor olaparib in HeLa and breast cancer cells." (PMID 34277417, 2021). "The role of USP9X in breast cancer and its spectrum of breast cancer targets have not been studied." (PMID 25606592, 2014).